MPPED2 (metallophosphoesterase domain containing 2)
Description:
Displays low metallophosphoesterase activity (in vitro). May play a role in the development of the nervous system.
Synonyms: 239FB; C11orf8; FAM1B; D11S302E; Hs.46638; dJ873F21.1; dJ1024C24.1
Tractability: PROTAC: its protein half-life has been measured.
Gene: Protein-coding gene on chromosome 11 (30,384,493 to 30,586,927, reverse strand). Ensembl gene ENSG00000066382.
Subcellular location (Human Protein Atlas): Nucleoli; Mitochondria; Vesicles
Gene Ontology:
Molecular function: protein binding; AMP binding; cyclic-nucleotide phosphodiesterase activity; GMP binding; manganese ion binding; phosphoric diester hydrolase activity; hydrolase activity
Genetic constraint (gnomAD): Loss-of-function variants: 3 observed, 22.48 expected, observed/expected ratio (o/e) 0.13, 90% interval 0.06 to 0.34. The upper end of that interval is the gene's LOEUF score, 0.34, which puts it in group 1 of 6, group 1 being the genes least tolerant of losing a copy. Missense variants: 251 observed, 350.67 expected, observed/expected ratio (o/e) 0.72, 90% interval 0.64 to 0.8. Synonymous variants: 125 observed, 137.53 expected, observed/expected ratio (o/e) 0.91, 90% interval 0.79 to 1.05.
Homologues: Orthologues: chimpanzee MPPED2 (100% identical), macaque MPPED2 (100% identical), pig MPPED2 (100% identical), rabbit MPPED2 (100% identical), mouse Mpped2 (99% identical), guinea pig MPPED2 (99% identical), rat Mpped2 (99% identical), tropical clawed frog mpped2 (98% identical), zebrafish mpped2a (93% identical), zebrafish mpped2 (89% identical), Caenorhabditis elegans T07D4.2 (46% identical), Drosophila melanogaster CG16717 (46% identical), and 2 more. Paralogues in human: MPPED1 (79% identical).
Diseases named in the same sentence as MPPED2 in open-access papers:
MPPED2 is named in the same sentence as 34 diseases in open-access papers, as found by Europe PMC text mining. Sharing a sentence is not in itself a finding about the gene and the disease. The quoted sentences say what the papers report.
migraine (5 papers, 2021 to 2023). "A recent biocomputational genetic association analysis of migraine and RA demonstrated that there is a phylogenetic relationship between the genes responsible for migraine and RA, such as SLC24A3 and HLA-B, MPPED2 and STAT4, and ATP1A2 and IL6R, respectively." (PMID 35281991, 2021).
neuroblastoma (5 papers, 2018 to 2020). Neuroblastoma (NB) is the most common solid, extracranial childhood tumor. "Furthermore, an upregulated expression of MPPED2 was associated with better outcomes in neuroblastoma patients." (PMID 31781170, 2019). "Although it has been reported that several PDE members are upregulated in cancer and have oncogenic activity, MPPED2 was found to be downregulated in several cancer types, such as neuroblastoma, cervical cancer and oral squamous carcinomas." (PMID 31181813, 2019). "Previous studies have evidenced MPPED2 downregulation also in neuroblastoma, cervical cancer, oral squamous carcinoma and thyroid cancer, indicating that its tumor suppressor activity is not confined to few neoplastic histotypes." (PMID 31181813, 2019). "Downregulation of MPPED2 has been demonstrated in neuroblastoma and breast cancer." (PMID 33680922, 2020). "Moreover, MPPED2 gene has been already reported to play an important anti-oncogenic role in oral squamous cell carcinoma, cervical cancer and neuroblastoma." (PMID 29783666, 2018). "A previous study has shown that MPPED2 functions as a tumor suppresser in neuroblastoma tumorigenesis, and thus the low expression of RP5-1024C24.1 might promote tumor progression." (PMID 29351231, 2018).
oral squamous cell carcinoma (5 papers, 2018 to 2024). "Down-regulation of the MPPED2 gene expression has been reported in several malignant tumors, including squamous cell carcinoma of the mouth, thyroid carcinoma (papillary variant), and cancer cervix." (PMID 39483945, 2024). "Inhibiting MPPED2 resulted in increased proliferation and migration of oral squamous cell carcinoma, suggesting anti-proliferative functions of the MPPED2 gene product." (PMID 31781170, 2019). "It is expressed ubiquitously in most human tissues, and the downregulated expression of MPPED2 has been reported in several malignant tumors, including oral squamous cell carcinoma, papillary thyroid carcinoma, and cervical cancer." (PMID 30846004, 2019). "Further, MPPED2 is downregulated in glioblastoma and thyroid neoplasia, acts as a tumor suppressor in breast cancer and oral squamous cell carcinoma, and the MPPED2 gene is differentially methylated in colorectal cancer and in individuals with gender incongruence." (PMID 37733787, 2023).
thyroid cancer (5 papers, 2018 to 2024). "Therefore, we decided to further investigate the functional role of the lncRNA RP5-1024C24.1 and its associated MPPED2 gene in human thyroid carcinomas and their possible relationship in thyroid cancer." (PMID 29783666, 2018). "Interestingly, the expression of MPPED2, its associated gene, was significantly decreased in the thyroid carcinoma samples analysed, suggesting a role of both these genes in thyroid carcinogenesis." (PMID 29783666, 2018). "Recently, our group has reported that MPPED2 is downregulated in benign and malignant thyroid neoplasia, and that its restoration in thyroid carcinoma cell lines reduced cell proliferation and migration." (PMID 31181813, 2019). "Accordingly, the stable restoration of both RP5-1024C24.1 and MPPED2 expression was able to attenuate proliferation and migration rate of thyroid cancer cell lines, suggesting a role of both these genes in thyroid cancer progression." (PMID 29783666, 2018). "Next, to characterize the role that this gene plays in thyroid carcinogenesis, we analysed by qRT-PCR the expression of MPPED2 in a panel of thyroid carcinoma cell lines and then we stably restored its expression in TPC-1 and FRO cell lines." (PMID 29783666, 2018). "Additionally, by analysing each thyroid carcinoma histotype, we found significant differences of MPPED2 expression between neoplastic and normal tissue samples." (PMID 29783666, 2018). "Co-expression network analysis showed that in thyroid cancer cells, ENST00000422494.1 was expressed in the same pattern as MPPED2, which has been widely reported to be overexpressed and to affect the malignancy of lesions in thyroid tissues." (PMID 29382910, 2018). "Moreover, the restoration of their expression in thyroid cancer cell lines reduces cell proliferation and migration, thus suggesting a tumour suppressor role for RP5-1024C24.1 and MPPED2 in the development of thyroid neoplasias." (PMID 29783666, 2018).
breast carcinoma (4 papers, 2015 to 2025). "MPPED2 upregulation inhibits glioblastoma cell proliferation and enhances temozolomide sensitivity, and it also functions as a tumour suppressor in breast cancer." (PMID 40591061, 2025). "Particularly in papillary thyroid carcinomas and breast cancer, MPPED2 expression has been reported to affect the malignancy of lesions." (PMID 25985088, 2015).
cervical cancer (4 papers, 2018 to 2024). A primary or metastatic malignant neoplasm involving the cervix. "Our work has brought to light, the association of MPPED2 protein with p16INK4A among high-risk HPV-induced cervical carcinoma." (PMID 39483945, 2024). "Hence, for the first time, we tried to find a correlation between p16INK4A and MPPED2 protein expression in those cervical carcinoma tissues, with evidence of a high-risk HPV viral genome." (PMID 39483945, 2024). "On the other hand, expression of MPPED2 was observed to be downregulated in different cancers like neuroblastoma, cancer of the cervix, squamous carcinomas of the mouth, and breast cancer." (PMID 39483945, 2024). "Recently, the expression of metallophosphoesterase-domain-containing protein 2 (MPPED2) was identified in cervical cancer." (PMID 39483945, 2024). "At the same time, an inverse correlation between the p16INK4A and MPPED2 protein levels expression in cervical carcinoma patients was also observed." (PMID 39483945, 2024). "Further studies need to be carried out in a larger population with more effective research tools to highlight the future therapeutic development of MPPED2 protein against cervical carcinoma." (PMID 39483945, 2024). "For the first time, we thus report a significant correlation between the p16INK4A and MPPED2 proteins in cervical carcinoma." (PMID 39483945, 2024). "We found a significant linear correlation (p=0.000) between the expression levels of p16INK4A and MPPED2 proteins in cervical carcinoma cases." (PMID 39483945, 2024). "The main aim of the study was the identification of MPPED2 protein expression and correlation it with p16INK4A protein for a future therapeutic approach in high-risk HPV-induced cervical carcinoma." (PMID 39483945, 2024). "Hence, in the present study, we try to see the expression of MPPED2 in human cervical carcinoma and its correlation with age and p16INK4A protein expression level." (PMID 39483945, 2024). "Therefore, we tried to correlate the expression levels of both p16INK4A and MPPED2 proteins in human cervical carcinoma tissues for the first time." (PMID 39483945, 2024). "However, no studies have been reported about the correlation of p16INK4A and MPPED2 proteins in cervical carcinoma tissue in humans." (PMID 39483945, 2024). "Our study found a linear relationship between the age and p16INK4A protein expression but not between the age and MPPED2 protein expression in cervical carcinoma patients." (PMID 39483945, 2024). "Although the expression of MPPED2 protein has been identified in many cancers, no studies have been carried out to determine its significance in cervical carcinoma." (PMID 39483945, 2024).
chronic kidney disease (3 papers, 2018 to 2025). Impairment of the renal function secondary to chronic kidney damage persisting for three or more months. "Among the putative human Six1 targets are also the metallophosphoesterase MPPED2, which has been associated with chronic kidney disease, and the serine/threonine kinase 39 (STK39), also called SPAK." (PMID 40213817, 2025). "A previous genome-wide association study suggested that MPPED2 influences the estimated glomerular filtration rate (eGFR) and appears to be associated with renal function in patients with chronic kidney disease." (PMID 31781170, 2019). "Previous GWAS studies and biomedical experiments reported that MPPED2 was associated with chronic kidney disease, and knockdown of this gene in zebrafish embryos suggested a role for it in renal function." (PMID 30263051, 2018). "The metallophosphoesterase MPPED2 is associated with chronic kidney disease." (PMID 40213817, 2025).
adenoma (2 papers, 2019 to 2024). A neoplasm arising from the epithelium. "We found that MPPED2 methylation pattern showed a stepwise increase from low-risk normal mucosa to high-risk normal mucosa, to hyperplastic polyp, to adenoma, and to carcinoma (P < 0.001)." (PMID 30846004, 2019). "The linear mixed-effects modeling analysis found that a cumulative pattern of MPPED2 methylation changes from normal mucosa to hyperplastic polyp to adenoma, and to carcinoma (P < 0.001)." (PMID 30846004, 2019). "Genome-wide methylation profiling has revealed a novel differentially methylated biomarker, metallophosphoesterase domain containing 2 (MPPED2), demonstrating methylation alterations across the progression from normal mucosa to hyperplastic polyps, adenomas, and carcinomas." (PMID 38464391, 2024).
aniridia (2 papers, 2011 to 2022). Aniridia is a congenital ocular malformation characterized by the complete or partial absence of the iris. "MPPED2, ALX4, and EXT2 are associated with WAGR syndrome (Wilms’ tumor, aniridia, genitourinary anomalies, and mental retardation), a developmental disorder." (PMID 36292693, 2022).
thyroid tumor (2 papers, 2009 to 2022). A benign or malignant neoplasm affecting the thyroid gland. "We also integrated differentially downregulated DEGs from the datasets and identified six downregulated DEGs, namely, MPPED2, TNFRSF11B, FHL1, CRABP1, MATN2, and TFF3, collectively known as thyroid tumor-downregulated genes (TTDGs)." (PMID 35990603, 2022). "Among these, metallophosphoesterase domain containing 2 (MPPED2) and cellular retinoic acid-binding protein 1 (CRABP1) under-expression have already been observed in thyroid tumours." (PMID 19809427, 2009).
prostate carcinoma (1 paper, 2019). A carcinoma that arises from epithelial cells of the prostate gland. "However, we could exclude MPPED2 downregulation as a feature of all human malignancies, since liver, lung and prostate carcinomas did not display any decrease of MPPED2 expression, as evaluated on TCGA dataset." (PMID 31181813, 2019).
Thyroid Diseases (1 paper, 2018). "To characterize the role of lncRNAs in thyroid carcinogenesis, we decided to focus our study on the lncRNA RP5-1024C24.1, located on chromosome 11 in antisense position with respect to the MPPED2 gene encoding a metallophosphoesterase protein." (PMID 29783666, 2018). "The positive correlation between RP5-1024C24.1 and MPPED2 expression was still significant when we consider only the thyroid malignant samples (PTC, FTC, ATC) (p = 0.0381)." (PMID 29783666, 2018). "Consequently, we evaluated the expression of the MPPED2 gene by qRT-PCR in the same set of thyroid neoplastic samples analysed for RP5-1024C24.1 expression: a reduced expression of this gene was observed in the different histotypes analysed." (PMID 29783666, 2018).
tumor (14 papers, 2017 to 2025). "This lncRNA is located on chromosome 11, in the antisense position with respect to the MPPED2 gene that encodes a metallophosphodiesterase protein, and it has been already reported as a candidate tumor suppressor in cervical cancer, neuroblastoma, glioblastoma, and oral squamous cell carcinoma." (PMID 35804851, 2022). "In conclusion, the results presented here indicate that the down-regulated RP5-1024C24.1 and its associated-gene MPPED2, could represent novel tumour suppressor genes with a considerable role in thyroid cell neoplastic transformation and progression." (PMID 29783666, 2018). "MPPED2 has been reported to act as a tumor suppressor that inhibits PTC via activation of PTEN and suppression of the AKT pathway." (PMID 35990603, 2022). "In conclusion, the results presented here support a tumor suppressor role of MPPED2 in breast carcinogenesis and propose the hypermethylation of its promoter as one of the main mechanisms accounting for its downregulation in BC." (PMID 31181813, 2019). "On the other hand, an increased expression of MPPED2 in tumor cell lines arrested the cell cycle of those cells and therefore impaired the proliferation." (PMID 31781170, 2019). "H-score analysis confirmed that MPPED2 expression was significantly reduced in tumor tissues (***, p < 0.001) and metastases (**, p < 0.01), compared with normal adjacent breast tissues." (PMID 31181813, 2019). "Specifically, our results provide the first evidence that tumor-specific hypermethylation in MPPED2 promoter occurs frequently in CRCs and its increasing accumulation means the further development of colorectal neoplasia." (PMID 30846004, 2019). "Recent studies have demonstrated that the expression of MPPED2 is drastically down-regulated in several malignant neoplasias originating from different tissues." (PMID 29783666, 2018). "Among them, we focused on the down-regulated RP5-1024C24.1 located in an antisense position with respect to the MPPED2 gene which codes for a metallophosphoesterase with tumour suppressor activity." (PMID 29783666, 2018). "However, as a member of metallophosphoesterase proteins, the related MPPED2 has been shown to have pronounced tumor suppressor activities." (PMID 33680922, 2020). "Moreover, MPPED2 expression negatively affected BC cell migration and invasion, supporting the anti-oncogenic role of MPPED2 in breast carcinogenesis." (PMID 31181813, 2019). "The aim of this study was to investigate whether the tumor suppressor role of MPPED2 described by our group in thyroid neoplasia could be extended to BC." (PMID 31181813, 2019). "Moreover, its restoration in cancer cell lines induces apoptosis and negatively modulates cell proliferation, thus proposing MPPED2 as a potential candidate tumour suppressor gene." (PMID 29783666, 2018). "Furthermore, miR-448 functions as a tumor promoter in OSCC through targeting MPPED2." (PMID 32787801, 2020). "Interestingly, very similar results were obtained when the same TC cells were transfected with MPPED2, thus validating the hypothesis that MPPED2-AS1 tumor suppressor activity occurs through the induction of MPPED2 expression by reducing its hypermethylation status." (PMID 35804851, 2022). "Finally, the physiological role of MPPED2 during normal development and in adult tissues is still far from being defined: the generation of knock out mice for the MPPED2 gene would surely give more information about the physiological role of MPPED2 and may even validate its tumor suppressor role." (PMID 31181813, 2019). "The metallophosphoesterase domain containing 2 protein (MPPED2) was shown to be a potent tumor suppressor involved in the downregulation of breast carcinogenesis and ADMC significantly upregulated (2.0 fold) it in tumor cells." (PMID 35574362, 2022).
tumor (continued). "Moreover, we found a significant (p = 0.0444) positive correlation between their expression in the whole neoplasm set analysed, suggesting that both RP5-1024C24.1 and MPPED2 are co-regulated during the process of thyroid carcinogenesis." (PMID 29783666, 2018). "Thus, we can speculate that MPPED2 expression reduces BC cell migration and invasion in vitro through the modulation of these canonical EMT markers, further supporting its anti-oncogenic role played in breast carcinogenesis." (PMID 31181813, 2019).
cancer (7 papers, 2017 to 2024). A tumor composed of atypical neoplastic, often pleomorphic cells that invade other tissues. "The MPPED2 gene regulates many cellular functions, including differentiation, proliferation, and cellular apoptosis—well known for the link between their malfunctioning and cancer pathogenicity." (PMID 34638449, 2021). "Therefore, in order to verify whether MPPED2 downregulation was a more general event in cancer, we evaluated MPPED2 expression in breast cancer (BC), aiming also to identify new players in breast carcinogenesis that might represent useful diagnostic markers." (PMID 31181813, 2019). "One recent computational study showed that both MPPED2 and RSPO3 play a role in carcinogenetic process across cancer types, which suggests that they might be part of the active processes underlying colorectal carcinogenesis." (PMID 30846004, 2019).
breast (2 papers, 2019). "The methylation status of MPPED2 increased significantly in each colorectal lesion groups (all P < 0.05), in comparison with their respective normal groups." (PMID 30846004, 2019).
MPPED2 also shares sentences with these, for which no sentence is quoted: colorectal cancer (3 papers); essential hypertension (2); glioblastoma (2); hyperplastic polyp (2); Hypertension (2); papillary thyroid carcinoma (2); autism (1); bacterial infection (1); coronary atherosclerosis (1); diabetes (1); endometriosis (1); infection (1); kidney damage (1); migraine with aura (1); migraine without aura (1); schizophrenia (1); type 2 diabetes (1); WAGR syndrome (1); Wilms tumor (1).